CD24 (CD24 molecule)
Diseases named in the same sentence as CD24 in open-access papers (continued):
Sharing a sentence is not in itself a finding about the gene and the disease.
tumor (continued). "In ER+ disease CD44+CD24-/low positive tumours were associated with ductal morphology with 81% of CD44+CD24-/low positive cases being ductal compared to 73% of CD44+CD24-/low negative cases (P = 0.012)." (PMID 22112299, 2011). "HCC with low NDRG2 expression was strongly associated with CD24 overexpression in tumor tissues (P = 0.04)." (PMID 21676268, 2011). "The presence of CD44-/CD24+ tumor cells was solely associated with strong HER2 staining (P = 0.002) and not with any other tumor characteristics." (PMID 18559090, 2008). "Interestingly, CD44hi/CD24hi cells exhibited a mesenchymal-type morphology and expressed higher levels of vimentin, consistent with our finding that CD44/CD24 coexpression in tumor cells was associated with vimentin-positive tumors." (PMID 40647395, 2025). "In addition to its association with tumor cells, CD24 has been found to bind to certain pathogens, including streptococcus pneumoniae, which utilizes CD24 as a receptor for adherence and invasion into host cells." (PMID 40486886, 2025). "This dichotomy underlies the complex role of CD24 in tumor immunology." (PMID 40647395, 2025). "Furthermore, CD24 exhibits a strong association with immune checkpoint genes, suggesting its potential role in modulating tumor immune infiltration." (PMID 40830893, 2025). "Many studies have shown a strong association between CD24 and chemoradiotherapy resistance in tumor cells, but the specific mechanism remains unclear." (PMID 40486886, 2025). "Notably, CD24 has also been implicated in modulating cellular senescence, a state of stable growth arrest often acting as a tumor-suppressive barrier." (PMID 40777020, 2025). "Interestingly, by combining the status of CD24 expression in tumor cells with the density of T-lymphocytes infiltrating the tumor—an immune-related marker—we identified a high-risk subgroup with the worst survival outcomes." (PMID 40647395, 2025). "Importantly, we also found that high CD44/CD24 coexpression in tumor cells was associated with worse DFS, MFS, and OS." (PMID 40647395, 2025). "The macrophage‐expressed inhibitory receptor Siglec‐10 engages with tumor‐associated CD24 through interactions at its extracellular domain, which triggers intracellular signaling via immunoreceptor tyrosine‐based inhibitory motifs (ITIMs) located within its cytoplasmic tail." (PMID 40529613, 2025). "CD24 is also associated with cancer stem cell properties, which may drive tumor recurrence and resistance to therapy." (PMID 40895068, 2025). "CD24 can directly regulate the malignant behavior of tumor cells and indirectly inhibit the function of immune cells in the meantime, which promotes the immune escape of tumor cells, induces cancer invasion and causes poor prognosis." (PMID 40486886, 2025). "It has been shown that patients without EGFR‐TKIs benefit more from immunotherapy compared with TKI experienced, since EGFR‐TKIs foster the TME associated with tumor immune escape via the innate immune signaling pathway of type I IFNs or upregulate innate immune checkpoint CD24." (PMID 40859900, 2025). "Additionally, this ecDNA carries the CD24, whose high expression has been linked to tumor cell growth, metastasis, and resistance to apoptosis." (PMID 41360770, 2025). "Consequently, the role of CD24 as a tumor marker offers potential in diagnostic, prognostic, and therapeutic strategies, highlighting the importance of further research to exploit the role of CD24 multifaceted functions in cancer biology." (PMID 38881902, 2024). "According to this study, CD24 is upregulated in tumor tissues and is associated with OS." (PMID 38217543, 2024). "Moreover, the presence of CD24 on the cell surface and in the cytoplasm is associated with poor prognosis, histology grades, tumor size, and lymph node positivity." (PMID 38881902, 2024).
tumor (continued). "As one of the most crucial biomarkers of cancers, CD24 is frequently highly expressed in solid tumors, while tumor-associated macrophages express Siglec-10 at high levels, Siglec-10 and CD24 can interact on innate immune cells to lessen inflammatory responses to a variety of disorders." (PMID 38279998, 2024). "Interestingly, targeting CD24 can enhance anti-tumor immune responses by inhibiting tumor-associated macrophages (TAM)." (PMID 38914670, 2024). "We also discovered a novel population of tumor-infiltrating CD24+ cancer-associated fibroblasts (CAFs), suggesting that the CD24/SOX4-centered signaling hub could be a potential therapeutic target." (PMID 38203779, 2024). "The expression of CD24 in various malignant tumors, such as breast, gastric, hepatocellular, and bladder cancers, is closely linked to tumor invasiveness, metastatic potential, and response to treatment, suggesting a pivotal role in tumor progression." (PMID 39184916, 2024). "Furthermore, blockade of CD24 interaction with Siglec-10, expressed by tumor-associated macrophages caused enhancement of phagocytic activity and reduction of tumor growth." (PMID 37346044, 2023). "Nevertheless, CD24-surfaced P-selectin also allows tumour cells to interact, causing the rolling of cancerous cells on vascular endothelium, thereby eventually leading to tumour dissemination." (PMID 38137380, 2023). "In addition, CD24 is associated with several cancer-related signalling pathways and closely interacts with other molecules and immune cells to influence tumour progression." (PMID 38137380, 2023). "Another noteworthy component of the "don't engulf me" signals is the CD24 molecule, which experiences an elevated expression in tumor cells found in organs such as the ovaries and breasts, prompting tumor-associated macrophages to express its corresponding ligand, Siglec-10." (PMID 37822610, 2023). "In a preclinical model of CD24+ solid tumours, the blockade of CD24‐Siglec‐10 interaction with anti‐CD24 mAb showed an increase in TAMs‐associated phagocytosis in vitro and TAMs‐dependent reduction of tumour growth and improvement of survival in vivo." (PMID 37654003, 2023). "In addition to inflammation, CD24 has been implicated in oncogenesis and tumor evasion of host immunity." (PMID 37228622, 2023). "Tumor CD24 expression has been linked with alterations in several oncogenic signaling pathways." (PMID 36013184, 2022). "Studies have also linked the MaSC hierarchy with the profile of tumor initiating cells/BCSCs characterized by CD44+/CD24- and ALDH+, where, CD44+/CD24- correspond to the MaSC population (EpCAMlow/-/CD49fhigh/+) and ALDH+ correspond to the luminal progenitor (EpCAMhigh/+/CD49fhigh/+) cells." (PMID 36157462, 2022). "In contrast to normal cells, where CD24 is primarily located in the external surface of the plasma membrane, cancerous cells also exhibit cytoplasmic CD24 accumulation, which has been associated with tumor progression, lymph node positivity, and patient survival." (PMID 36294907, 2022). "Moreover, CD24 has been implicated in tumor metastasis, as fucosylated CD24 interacts with P‐ and E‐selectin, allowing invasion of tumor cells to distal sites." (PMID 34293822, 2022). "CD24 is associated with poor prognosis in several forms of tumor tissues." (PMID 36497321, 2022). "The expression of GRAMD1C, NFKBIA, and ACSS2 was significantly higher in normal tissues than in tumour tissues (P < 0.001, P = 0.0096, and P < 0.001, respectively), which indicated that CD24 and INHBA were risk genes and that GRAMD1C, NFKBIA, and ACSS2 were protective genes." (PMID 35999846, 2022). "Given that tumor-associated macrophages (TAMs) can mediate cancer metastasis, chemotherapeutic resistance, and immune evasion through secreting CD24, CXCL8, CCL2, and other cytokines, SLC1A5 is probably involved in the formation of the immune-tolerant microenvironment." (PMID 35419359, 2022).
tumor (continued). "More factors are associated with poor prognosis besides CD44/CD24 and basal-like tumor features." (PMID 36120232, 2022). "In addition, the CD24/Siglec-10 interaction has been implicated in tumor immune evasion, inhibiting macrophage-mediated phagocytosis as well as natural killer (NK) cell cytotoxicity." (PMID 36013184, 2022). "Furthermore, CD24 was reported to cause chemotherapy resistance and regulate various signaling pathways in diverse types of tumor cells." (PMID 36497321, 2022). "Several studies have shown that increased expression of CD24 is associated with tumor progression." (PMID 34442367, 2021). "CD24 has recently been uncovered as a novel putative “don't eat‐me” signal, which is upregulated in the tumor compartment and helps tumors escape phagocytosis by binding tumor‐associated macrophages to SIGLEC‐10 on the surface of macrophages." (PMID 33650762, 2021). "According to our data, CD24 translocation could represent a more global phenomenon linked to tumor cell plasticity that may overtake specific mechanism of resistance." (PMID 34426608, 2021). "Additionally, the SIGLEC10 expressed by tumor-associated macrophages can interact with CD24 to promote immune evasion." (PMID 33796453, 2021). "Finally, loss of Annexin A1 resulted in the loss of a discrete CD24+/Sca1− population containing putative tumor initiating cells." (PMID 33800279, 2021). "Interestingly, the combination of PTX with TQ significantly abolished the tumor-associated stem cell clone (CD44+/CD24-) by 32.3 ± 0.08%." (PMID 31968657, 2020). "Moreover, CD24 expression is associated with tumor number, tumor size, vascular invasion, encapsulation, differentiation, satellite lesions, and poor TNM stage in overall and relapse-free survival." (PMID 32466488, 2020). "Besides, CD24 had been shown to serve as a candidate unique identifier for CSCs in NB, where a small fraction of CD24+ cells were observed within the high-risk NB tumor-spheres derived from bone marrow aspirates." (PMID 31191243, 2019). "Additionally, primary NB cell lines taken from bone marrow metastases revealed that overexpression of the CD24 glycoprotein in cancer cells is associated with accelerated tumor formation and growth." (PMID 31191243, 2019). "We investigated whether the loss of IGF-1R function altered IL-6 expression in the tumor epithelial cell population by measuring IL-6 expression in the CD24+/CD29lo (luminal) and CD24+/CD29hi (basal) cell populations." (PMID 30458886, 2018). "In contrast, the tumor cells in the Cd24-deficient mice exhibit large and pleomorphic nuclei." (PMID 29423273, 2018). "The slight decline in CD44/CD24 might be due to the different microenvironment between the tumor and the liver that caused the CSC phenotypic plasticity." (PMID 29062075, 2017). "In addition, the blood-based diagnosis of OC via three exosomal protein markers for tumor (CA125, EpCAM, and CD24) showed significant diagnostic power in that tumor testing with a drop of blood was possible." (PMID 28506269, 2017). "Though, accumulated evidences suggested that CD24 was associated with carcinogenesis and cancer metastasis, it was still unclear whether CD24 could change angiogenesis resulting tumor metastasis in CRC." (PMID 27494878, 2016). "In order to identify transcripts that may be elucidated for the specific effect of IGF1R on CD24+ tumorigenic capacity we screened by qtPCR analysis several transcripts that are associated with tumor growth and metastasis." (PMID 27179633, 2016). "Also, a causal role of Notch-Jagged signalling in mediating tumour-initiation potential and/ or drug resistance of the CD24+ CD44+ hybrid E/M cells remains to be directly tested." (PMID 27170649, 2016). "Interestingly, a membrane circumference CD24 expression, as observed in these ‘induced’ cells, is implicated in tumour progression and poor prognosis." (PMID 25669750, 2015).
tumor (continued). "CD44+/CD24+ profiles was associated with tumor size and lymph node metastasis." (PMID 23419168, 2013). "Furthermore, using the PCR and intracellular signaling array systems, it was observed that numerous tumor metastasis-associated genes and intracellular signaling molecules in the CD24+ cells are upregulated." (PMID 24179538, 2013). "Moreover, CD24 and Src expression positively correlated with each other, and miR-34a expression was negatively associated with Src in the tumor tissues." (PMID 23533633, 2013). "Specifically, miRNA-34a suppresses expression of CD24 and Src, thereby diminishing the tumor progression-associated functions of these genes, which results in reduced expression of the oncomir miR-21, and thus relieves miR21-mediated repression of Pdcd4 and PTEN expression." (PMID 23533633, 2013). "In many tumor types, CD24 expression is associated with metastasis." (PMID 23947765, 2013). "Kaplan-Meier analysis showed that the presence of CD44+/CD24-/low tumor cells was significantly associated with shorter OS compared with the absence of CD44+/CD24-/low tumor cells (39.3 ± 2.6 months versus 54.0 ± 3.5 months; Pearson chi-square, 12.140, p = 0.001)." (PMID 22762532, 2012). "CD24 expression also showed a marginal association with larger tumours." (PMID 22333601, 2012). "In addition, we found that CD44+CD24-/low tumours were associated with the luminal 1b subtype which, like basal-like tumours, is a subtype defined by basal cytokeratin expression." (PMID 22112299, 2011). "Since the CD44+/CD24− signature has been associated with tumor initiation, the up-regulation of CD24 population suggest that ATF-126 could decrease the tumor initiating ability of the original line MDA-MB-231." (PMID 21931769, 2011). "Numerous studies have linked CD24 with tumorigenesis and tumor progression." (PMID 21359202, 2011). "Beyond direct tumor targeting, Siglec blockade (e.g., anti-Siglec-7/-9/-10) can restore NK/T cell cytotoxicity, while interventions against tumor-associated sialoglycans (e.g., CD24-Siglec-10, GD3-Siglec-7) may enhance phagocytosis and NK activity." (PMID 41154604, 2025). "Furthermore, CD24 has been implicated in lymphangiogenesis, a key process in tumor metastasis, suggesting its involvement in modulating lymphatic vessel formation and function within the tumor microenvironment." (PMID 40895068, 2025). "However, the direct impact of CD24 loss on tumor cell susceptibility to immune effectors such as macrophages, cytotoxic T cells, and Natural Killer (NK) cells, as well as its specific contribution to establishing an immunosuppressive TME remains unexplored and requires further investigation." (PMID 40783744, 2025). "Preclinical studies have demonstrated that CD24 promotes immune evasion in ovarian cancer and triple-negative breast cancer by interacting with the inhibitory receptor sialic acid binding ig-like lectin 10 (Siglec-10) expressed by tumor-associated macrophages (TAMs)." (PMID 38787372, 2024). "In addition, we investigated whether the degradation of the CD24 protein in HCC cells affects tumor‐associated macrophages in the tumor microenvironment." (PMID 36866919, 2023). "In addition, tumor-expressed CD24 promotes immune evasion by interacting with the inhibitory receptor sialic acid-binding Ig-like lectin 10 (Siglec-10) expressed as an anti-phagocytic signal by tumor-associated macrophages (TAMs)." (PMID 38259511, 2023). "Therefore, the microenvironment of TSC2-deficient tumor cell might promote high expression of CD24 in macrophages to induce autoimmune escape." (PMID 36231025, 2022).
tumor (continued). "We have previously reported that evaluating CD24 levels in peripheral blood leukocytes (PBLs) can serve as a potential promising screening tool to select which healthy subjects are in fact at risk of having CR neoplasia and need to undergo screening colonoscopy." (PMID 34442367, 2021). "It has been demonstrated that ascitic fluid from ovarian cancer patients contains EVs which may promote tumor cell migration necessary in metastasis by transferring molecules such as CD24 and EpCAM to recipient cells which are associated with increased tumor invasiveness." (PMID 34572444, 2021). "Presently, tumor immune escape is a hallmark of tumor growth and involves tumor expression of inhibitory immune checkpoints or “don’t eat me” signals such as programmed cell death ligand 1 (PD-L1), β2-microglobulin (β2 m), CD24, and CD47 to evade immune responses." (PMID 34827170, 2021). "Therefore, we speculated that some subjects with CR neoplasia with low CD24 expression may carry CD24 genetic variants." (PMID 26078485, 2015). "To clarify the controversies, we have implemented knockdown and expression strategies on murine models to elucidate the modulation efficacies of CD24 in oncogenesis and tumor immunity." (PMID 41585138, 2026). "Tumor cells express Siglec ligands, such as CD24, which specifically bind to Siglec-10 receptors on immune cells." (PMID 41584035, 2026). "When the TetOFF-CD24 grafts became discernible under fluorescence detection, Doxy was administered to mice six times to evaluate the potential of CD24 in affecting tumor growth." (PMID 41585138, 2026). "Stemness-associated genes such as GDF15, ALDH1L1, GPC3, AFP, EPCAM, CD44, and CD24 were predominantly expressed in tumor cells, with varying levels across other cell types including CAFs, TECs, and TAMs." (PMID 41493679, 2026). "These cells interact with CD24, a so called "don't eat me signal" expressed on tumor cells, through Siglec-10, a receptor that contributes to immune evasion by promoting an immunosuppressive environment." (PMID 41606146, 2026). "This platform leverages localized viral delivery to selectively downregulate "don't eat me" signals (CD47 and CD24) on tumor cells, thereby restoring macrophage phagocytic capacity." (PMID 42003796, 2026). "This study demonstrates that SLC38A4 promotes Kupffer cell phagocytosis and restricts tumor liver metastasis by suppressing CD24." (PMID 42067616, 2026). "In ovarian cancer, TAM‐derived extracellular vesicles upregulate GATA‐binding protein 3 (GATA3) by activating the CD24/sialic acid‐binding IgG‐like lectin 10 (Siglec‐10) axis, promoting the immune escape of tumor cells." (PMID 41426206, 2026). "CD24 has recently been identified as a central molecule in tumor immune evasion by interacting with Siglec-10 on macrophages in human, sending a “don’t eat me” signal that prevents phagocytosis." (PMID 40783744, 2025). "Overexpression of miR-10a-5p was found to downregulate STAT3 phosphorylation, TFR1, and CD24 expression, indicating that miR-10a-5p influences tumor immune escape via the TFR1/STAT3 axis." (PMID 41551164, 2025). "Blocking CD24 or Siglec‐10 expression by gene or antibody facilitates macrophage phagocytosis and inhibits tumor growth." (PMID 40529613, 2025). "Although CD24 expression is linked to aggressive tumor behaviour, in vitro gastric CSCs typically exhibit a CD44-positive/CD24-low phenotype." (PMID 40866457, 2025). "As a rising immune checkpoint on tumor cells, CD24 is closely related to tumorigenesis and progression." (PMID 40486886, 2025). "Interfering with CD24 or Siglec-10 has been shown to significantly enhance macrophage phagocytosis of CD24-positive tumors, thereby inhibiting tumor growth." (PMID 40260303, 2025). "In our previous work, we identified CD24 as a highly glycosylated and variably expressed protein overexpressed in various tumors and tumor-initiating cells." (PMID 41281650, 2025).